S1PR1 (sphingosine-1-phosphate receptor 1)
Diseases named in the same sentence as S1PR1 in open-access papers (continued):
Sharing a sentence is not in itself a finding about the gene and the disease.
breast cancer (continued). "In breast cancer, low S1PR1 expression induces the formation of vasculogenic mimicry (VM), which consists of vessel-like networks associated with poor prognosis and the development of tumor metastases." (PMID 36835432, 2023). "Through the effect of S1PR1, obesity can lead to an increase in inflammation and breast cancer proliferation as well." (PMID 33758708, 2021). "Along with the cytokines mentioned before, a recent study found a correlation between IL-22 receptor and S1PR1 in highly metastatic, advanced breast cancer tumors." (PMID 33758708, 2021). "Here, we determined that the level of S1PR1 in breast cancer cells is positively correlated with STAT3 activation and VEGFA expression." (PMID 34059068, 2021). "A high expression of S1PR1 predicts poor prognosis in breast cancer patients and gastric cancer patients." (PMID 34113619, 2021). "It has been shown that there is a negative correlation between the expression levels of miR-542-3p and S1PR1 in breast cancer tissue and cell line." (PMID 35201458, 2021). "Breast cancer cells significantly reduce the expression of miR-542-3p, while the expression of S1PR1 is upregulated, depicting a yin yang relationship." (PMID 35201458, 2021). "To evaluate the mechanism by which S1PR1 affects the progression of breast cancer, we used small interfering RNA (siRNA) to inhibit the S1PR1 expression in breast cancer cells (MCF-7 and MDA-MB-231) and HUVECs." (PMID 34059068, 2021). "A preclinical study detected the function of S1PR1-antibody on the growth of breast cancer cell lines MDA-MB-231 and SK-BR-3." (PMID 34283088, 2021). "We further verified the significant reduction of S1PR1 expression in breast cancer and lung cancer patients through TCGA analysis." (PMID 32799825, 2020). "Prognostic data from Kaplan-Meier plotter showed that low levels of S1PR1 are significantly related to poor prognosis in breast cancer and lung cancer." (PMID 32799825, 2020). "We further evaluated the correlations between S1PR1 and markers of various immune cells in breast cancer and lung cancer using TIMER and GEPIA databases." (PMID 32799825, 2020). "Given our observations of the elevated co-expression of IL-22R1 and S1PR1 in aggressive human breast cancer, we further compared their expression between high and low metastatic breast cancer cell lines." (PMID 31935914, 2020). "Collectively, these results suggest that IL-22R1 and S1PR1 are elevated in breast cancers with bone metastatic properties." (PMID 31935914, 2020). "A preclinical study on human breast cancer cells found that S1PR1 antibody can enhance the cytotoxic and anti-proliferative effect of carboplatin on MDA-MB-231 and SK-BR-3 (HER2 subtype) cells, respectively." (PMID 32799825, 2020). "Estrogen (the growth-stimulating hormone in breast cancer cells) was shown to stimulate endothelial cell growth via S1PR1." (PMID 32799825, 2020). "Taken together, these data confirmed the down-regulation of S1PR1 expression in breast cancer and lung cancer patients." (PMID 32799825, 2020). "In comparison with normal control tissues, breast cancer and lung cancer tissues presented lower expression of S1PR1, which was also observed by GEPIA analysis." (PMID 32799825, 2020). "We further revealed that patients with IL-22Rhigh breast cancers displayed poorer survival rates compared to those with IL-22Rlow tumors and that the IL-22R level exhibited a positive relationship with S1PR1 expression." (PMID 31935914, 2020). "We used the Kaplan-Meier plotter to study the relationship between S1PR1 expression and clinical characteristics in patients with breast cancer and lung cancer." (PMID 32799825, 2020). "This shows that S1PR1 defects promote the occurrence of VM, and the knockout of S1PR1 in breast cancer cells increases the number of VMs." (PMID 32799825, 2020). "We used the Kaplan-Meier plotter database to further examine the prognostic value of S1PR1 in breast cancer." (PMID 32799825, 2020).
breast cancer (continued). "A limitation of our study was the lack of in vitro and animal experiments to confirm the role of S1PR1 in the growth and progression of breast cancer and lung cancer and its relationship with the infiltration of immune cells in the tumor microenvironment." (PMID 32799825, 2020). "We used the LinkedOmics function module to detect the S1PR1 regulatory network to further understand the biological role of S1PR1 in breast cancer and lung cancer." (PMID 32799825, 2020). "Accordingly, S1PR1 presumably plays a critical part in immune infiltration and acts as a prognostic marker in breast cancer and lung cancer." (PMID 32799825, 2020). "Cell lines with high and low S1PR1 expression were selected from several breast cancer cell lines (HS-578T, MDA-MB-231, MCF-7, T-47D, and BT-474)." (PMID 30814488, 2019). "Previous studies have demonstrated that upregulation of S1PR1 was found in some solid human cancers, including breast cancer, gastric cancer and hepatocellular carcinoma (HCC)." (PMID 31438989, 2019). "In breast cancer, the SphK1/S1P/S1PR1 axis is critically involved in regulating numerous cellular processes, including cell growth, survival, invasion, vascular integrity, immune cell trafficking, angiogenesis, and cytokine and chemokine production." (PMID 31807117, 2019). "The S1PR1 protein was highly expressed in 63 of the 100 breast cancer sample tissues and weakly expressed in the remaining 37 samples." (PMID 30814488, 2019). "The S1PR1 expression levels in breast cancer samples were analyzed in the context of the detailed clinical and pathological information." (PMID 30814488, 2019). "In the immunohistochemical analysis of human breast cancer tissue, S1PR1 expression was closely related to lymphatic metastasis." (PMID 30814488, 2019). "Down‐regulation of S1PR1 expression was found in breast carcinoma 54 and low levels of S1PR1 were correlated with higher proliferation of glioma cells and are a predictor for poor survival of glioblastoma patients." (PMID 27239439, 2016). "Previously, we have reported that in inflammatory carcinogenesis and obesity-mediated breast cancer, S1P exacerbates cancer progression through a positive-feedback mechanism mediated by S1PR1 and Stat3 and that FTY720 inhibits tumor growth by blocking this pathway." (PMID 40528704, 2025). "Since it was reported that S1P, as the ligand of S1PR1, could continuously activate S1PR1, leading to S1PR1 overexpression in breast cancer, we added S1P to ECs to investigate its effect on S1PR1 expression." (PMID 36068200, 2022). "The role of S1PR1 in the accumulation of tumor-specific Tregs was underpinned in studies with breast cancer patients, demonstrating that S1PR1-dependent decreased Treg levels in the bone marrow correlated with increased tumor antigen-specific Treg redistribution to the tumor." (PMID 35163211, 2022). "We hypothesize that S1PR1 could serve as a potent antitumor and antiangiogenic target in breast cancer by downregulating the P-STAT3/VEGFA pathway." (PMID 34059068, 2021). "Taken together, it is believed that SPHK1/S1P/S1PR1 axis by interacting with inflammatory cytokine amplification loops, could have prominent roles in the progression of inflammation-driven breast cancers." (PMID 34820423, 2021). "Furthermore, studies have suggested that SPHK1/S1P/S1PR1 signaling pathway also aids to mediate treatment-induced inflammation and resistance to doxorubicin and tamoxifen in breast cancer, which is also accompanying with upregulation of NF-κB/IL-6/STAT3." (PMID 34820423, 2021). "In summary, our work demonstrates that suppressing S1PR1 could inhibit the malignant progression of breast cancer, and the regulatory effect is achieved by regulating the S1PR1/P-STAT3/VEGFA pathway." (PMID 34059068, 2021). "Importantly, IL-22 stimuli promoted the expression of IL-22R1 and S1PR1 in aggressive MDA-MB-231 breast cancer cells." (PMID 31935914, 2020).
breast cancer (continued). "In addition, there was a positive correlation between the expression of IL-22R1 and S1PR1 in bone or brain metastases in breast cancer patients." (PMID 31935914, 2020). "We examined whether the IL-22 dependent induction of S1PR1 expression in MDA-MB231 breast cancer cells also occurs in macrophages." (PMID 31935914, 2020). "Taken together, these results indicate that IL-22 may serve as an important determinant of S1PR1 induction in breast cancer cells." (PMID 31935914, 2020). "Indeed, both IL22R1 and S1PR1 expression is elevated in invasive breast tumor specimens and bone metastatic breast cancer cells." (PMID 31935914, 2020). "The S1PR1 signaling can regulate the survival of breast cancer cells, which can increase the survival of breast cancer cells by downregulating the pro-apoptotic protein Bim and upregulating the anti-apoptotic protein Mcl-1, respectively, in ERK and PKC-dependent manner." (PMID 33101013, 2020). "Furthermore, the relationship between S1PR1 and specific immune infiltrates in breast cancer and lung cancer were analyzed." (PMID 32799825, 2020). "This further confirms that S1PR1 is significantly related to immune infiltrating cells in lung and breast cancer, suggesting that high levels of S1PR1 could induce immune activity in the lung and breast cancer microenvironment." (PMID 32799825, 2020). "Therefore, further research is needed to verify the role of S1PR1 in breast cancer and lung cancer using these models." (PMID 32799825, 2020). "Moreover, MDA-MB231MT, subclone of breast cancer cell lines that can form metastases in the bones expressed higher levels of IL-22R1 and S1PR1 than those of MDA-MB231 cell line." (PMID 31935914, 2020). "Experimental evidence implicated S1PR1 coupled to Gi and persistently triggered STAT3, mitogen-activated protein kinase (MAPK) and AKT signaling pathways, to promote many types of tumor growth and metastasis including breast cancer." (PMID 33101013, 2020). "Knockdown of S1PR1 in breast cancer cells increased the amount of VM." (PMID 30814488, 2019). "We confirmed that S1PR1 overexpression in breast cancer increased VEGF expression and secretion." (PMID 30814488, 2019). "Moreover, the low expression of S1PR1 correlates with VM and poor prognosis in breast cancer patient." (PMID 30814488, 2019). "S1PR1 may provide a new thinking direction for antiangiogenic therapy for patients with breast cancer." (PMID 30814488, 2019). "Thus, in breast cancer with high S1PR1 expression, antiangiogenic drugs should combine anti-EDV with anti-VM." (PMID 30814488, 2019). "In estrogen receptor positive (ER+) tumors high S1PR1 and S1PR3 were reported to be causally associated with tamoxifen resistance and poor prognosis, and in vitro, in ER+ MCF-7 breast cancer cells, the SphK1/S1PR3 loop promoted breast cancer progression and migration." (PMID 28415564, 2017). "Moreover, studies have shown that S1PR1 induces chemoresistance in breast cancer." (PMID 34059068, 2021). "Moreover, analysis of the Oncomine database indicated that the S1PR1 expression level was higher in breast cancer than in normal tissues, which suggests that S1PR1 could be a novel target for breast cancer treatment." (PMID 34059068, 2021). "However, some literatures have reported the oncogenic role of S1PR1 in breast cancer." (PMID 32799825, 2020). "A Gene Ontology (GO)-based gene set enrichment analysis (GSEA) showed that genes that are co-expressed with S1PR1 are enriched for vasculogenesis and the purinergic receptor signaling pathway, while genes related to mitochondria and RNA transcript processing were inhibited in breast cancer." (PMID 32799825, 2020). "Therefore, we use TIMER to investigate whether the expression of S1PR1 in breast cancer and lung cancer is related to immune infiltration." (PMID 32799825, 2020).
breast cancer (continued). "Notably, metastatic breast carcinomas expressed elevated S1PR1 compared to invasive metastatic breast carcinomas, indicating that elevated S1PR1 may correlate with metastatic breast tumors but not in primary breast tumors (right)." (PMID 31935914, 2020). "In this study, we found that S1PR1 could induce the switch in human breast cancer." (PMID 30814488, 2019). "However, whether S1PR1 in breast carcinoma can recruit lymphocytes to promote the secretion of angiogenesis-related factors by lymphocytes is unknown." (PMID 30814488, 2019). "The expression of S1PR1 and S1PR3 is often higher in breast cancer, suggesting that signaling through these receptors contributes to cancer growth and invasion." (PMID 38542328, 2024). "The SphK1-S1P-S1PR1 axis has emerged to be one of the major targets in developing anticancer agents against breast cancer, and quite a few SphK1 inhibitors such as SK1-I and S1PR1 antagonists such as NIBR0213 have been developed." (PMID 37220155, 2023). "The role of S1PR1 in tumour formation is consistent with the finding of S1PR1 upregulation in STAT3-positive tumours and in oestrogen receptor-positive breast cancer cells." (PMID 35563301, 2022). "Many have also attempted to investigate the involvement of S1PRs in the signaling cascades of SPHK1/S1P axis in human cancers, whereby substantial evidence has highlighted the interactions between SPHK1/S1P axis with S1PR1, S1PR3, and S1PR4 in breast cancer." (PMID 34820423, 2021). "Moreover, our study found that downregulating S1PR1 in MCF-7 and MDA-MB-231 cells could restore the chemosensitivity of the two cell types to DOX and DDP, which suggests that S1PR1 is associated with chemoresistance in breast cancer." (PMID 34059068, 2021). "RT-PCR suggested that BAF312 downregulated S1PR1 mRNA levels in breast cancer cells and HUVECs, and Western blotting assays indicated that BAF312 decreased the level of S1PR1 at the protein level." (PMID 34059068, 2021). "The study found that by depleting S1PR1, EDV was impaired while VM intensified, leading to a worse prognosis in breast cancer." (PMID 33758708, 2021). "A study reinforced the importance of S1PR1 and S1PR3 in breast cancer growth and adhesion by silencing the genes for these two receptors, resulting in a statistically reduced growth in the breast cancer tumors." (PMID 33758708, 2021). "BAF312 was the selected agonist of S1PR1, and we tested the anticancer efficacy of BAF312 in affecting breast cancer cells and HUVECs." (PMID 34059068, 2021). "In breast cancer, incessant activation of STAT3 appears to be attributable to the upregulation of the pro-inflammatory cytokine IL-6 and S1PR1." (PMID 34820423, 2021). "First, S1PR1 signaling in T cells enhances the tumor infiltration of Treg in a STAT3-dependent manner, reducing CD8 + TIL and increasing breast cancer and melanoma growth in mice." (PMID 31974367, 2020). "S1PR1 regulated RhoA activation to accelerate VE-cadherin phosphorylation (Y731), leading to increased EDV and reduced VM in human breast cancer cells." (PMID 30814488, 2019). "The aim of this study is to investigate S1PR1 on the regulation of EDV and mimicry formation in breast cancer." (PMID 30814488, 2019). "The results show that S1PR1 regulated RhoA activation to accelerate VE-cadherin phosphorylation (Y731), leading to increased EDV and reduced VM in breast cancer." (PMID 30814488, 2019). "Elevated S1P will interact with S1PR1 and S1PR3 and activate PI3K/Akt, Ras/ERK, PLC/PKC and Rho/ROCK signaling pathways, which, in turn, would promote proliferation, survival, growth, migration and metastasis of breast cancer cells." (PMID 37220155, 2023). "Macrophage-specific S1PR1 signaling promoted NLR family pyrin domain containing 3 (NLRP3) expression leading to enhanced IL-1β production via the inflammasome, which resulted in enhanced lymphangiogenesis and tumor metastasis in a murine breast cancer model." (PMID 35163211, 2022).
breast cancer (continued). "Interrupting the expression of S1PR1 could inhibit the growth of human breast cancer cells (MCF-7 and MDA-MB-231) and suppress the angiogenesis of human umbilical vein endothelial cells (HUVECs) via affecting S1PR1/P-STAT3/VEGFA axis." (PMID 34059068, 2021). "In addition, the TIMER database showed that S1PR1 and STAT3 had positive connections in breast cancer, and STAT3 and VEGFA were positively connected." (PMID 34059068, 2021). "We found a significant negative correlation between the S1PR1 expression level and tumor purity in both breast cancer and lung cancer (Left)." (PMID 32799825, 2020). "Our findings thus indicated that elevated IL-22R1, S1PR1, and MMP-9 expression may result in poorer survival in cases of relapsed breast cancer." (PMID 31935914, 2020). "Moreover, we observed the positive correlation between the expression of S1PR1 and CD68 and between IL-22R1 and CD68 in bone or brain metastases in breast cancer patients." (PMID 31935914, 2020). "Gene expression data demonstrated that clinical breast cancer tissues from patients with a bone or brain metastatic status had higher IL-22R1 and S1PR1 levels compared to non-mineral metastatic breast cancer cases (p < 0.05)." (PMID 31935914, 2020). "To determine the potential involvement of elevated IL-22R1 and S1PR1 expression in breast cancer metastasis to distant organs, we analyzed a cohort of 65 breast cancer patients harboring a metastasis at a non-mineral site (lung and liver), brain, or bone." (PMID 31935914, 2020). "Next, the role of IL-22R1, S1PR1, and MMP-9 in breast cancer progression and the potential prognostic value of assaying these factors were evaluated through the immunohistological staining of adjacent normal, invasive breast carcinoma, and metastatic breast carcinoma tissues." (PMID 31935914, 2020). "In addition to the S1PR1 axis, IL-22 stimulated the expression of matrix metalloproteinase-9 (MMP-9), thereby promoting breast cancer cell invasion." (PMID 31935914, 2020). "Statistical analysis of the immunohistochemical staining showed that VE-cadherin was highly expressed in the S1PR1-negative breast cancer tissues, and VE-cadherin was expressed at a low level in the S1PR1-positive breast cancer tissues (p = 0.013)." (PMID 30814488, 2019). "Meanwhile, β-catenin was highly expressed in the S1PR1-positive breast cancer tissues, and was expressed at a low level in the S1PR1-negative breast cancer tissues (p = 0.020)." (PMID 30814488, 2019). "Moreover, S1PR1 can stably activate STAT3 in tumor and bone marrow cells, which is essential for breast cancer cell proliferation, invasion and metastasis." (PMID 30498398, 2018). "IL22R1 and S1PR1 transcripts were detectable at only low levels in low metastatic breast cancer cell lines (MCF-7, T47D, MDA-MB453, and SKBR3) but showed robustly increased levels in the highly metastatic breast cancer cell lines (HCC1954, MDA-MB231, and MDA-MB157) as determined by qPCR." (PMID 31935914, 2020).